TG (thyroglobulin)
Diseases named in the same sentence as TG in open-access papers (continued):
Sharing a sentence is not in itself a finding about the gene and the disease.
tumor (343 papers, 1985 to 2026). "Both mutations were linked to tumor size, thyroglobulin levels, recurrence/metastasis, and higher recurrence risk, with co-mutation accelerating recurrence." (PMID 40988283, 2025). "Advanced tumor stage is also associated with a significantly higher risk of mortality, as are elevated levels of thyroglobulin and calcitonin." (PMID 39767732, 2024). "Patients with the mutation had noticeably higher mean levels of thyroglobulin and calcitonin, suggesting more intense tumor activity or a larger tumor mass." (PMID 39767732, 2024). "For patients without the BRAF mutation, there is a progressive increase in thyroglobulin and calcitonin levels with the advancing tumor stage." (PMID 39767732, 2024). "Initial work-up revealed a BRAF V600E mutated tumor and a pre-operatory thyroglobulin level of 262 μg/L (normal value < 58 μg/L)." (PMID 37191938, 2023). "Compared to the lower PLR group, the higher group was significantly associated with gender, tumor size, N stage and thyroglobulin level." (PMID 38161980, 2023). "Compared to the lower PLR group, the higher group was significantly associated with gender, tumor size, N stage and thyroglobulin level (P<0.05)." (PMID 38161980, 2023). "The definition of RAIR has been outlined in the 2015 ATA guidelines, which are mainly based on imaging manifestation characterized by the loss of radioiodine uptake and increasing level of the tumor marker thyroglobulin (Tg)." (PMID 36843580, 2023). "Radioactive iodine (RAI) is used in the adjuvant setting for patients with high-risk characteristics such as tumor size >2 cm, positive margins, cervical lymph node metastases, microvascular invasion, or postoperative thyroglobulin levels > 1 ng/mL." (PMID 36407154, 2022). "Consistent with this, in parallel, RNA-seq of 28 overlapping tumor samples, we observed down-regulation of thyroglobulin (encoded by the TG gene; q = 0.03; fig." (PMID 35731870, 2022). "Taken together, these results suggest that preoperative thyroglobulin level is significantly associated with tumor burden and tumor extent." (PMID 32182688, 2020). "In this study, we examined the association between preoperative serum thyroglobulin levels, tumor burden, and extent of DTC." (PMID 32182688, 2020). "Following tumor resection, delivery, and thyroidectomy, she underwent evaluation with stimulated thyroglobulin testing and diagnostic staging sodium iodide-131 scan (I-131), which revealed the presence of skeletal metastases." (PMID 29946481, 2018). "The tumor consisted of highly pleomorphic, undifferentiated cells with large zones of necrosis and loss of thyroid transcription factor-1 and thyroglobulin expression." (PMID 21912554, 2011). "Tumor-staging and measuring the tumor marker thyroglobulin allow for risk-adapted stratification." (PMID 40283881, 2025). "In a low–intermediate-risk tumor with high thyroglobulin levels, RAI could be used for ablative purposes." (PMID 39272954, 2024). "If the patient has a low–intermediate-risk tumor and a high post-surgical thyroglobulin level, RAI may be used for ablative purposes." (PMID 39272954, 2024). "NIS mRNA levels have been linked to both TSHR mRNA and tumour marker Thyroglobulin mRNA levels." (PMID 37352166, 2023). "Furthermore, thyroglobulin levels in urinary exosomes increased after tumor removal in patients with high risk of recurrence, proving exosomal thyroglobulin as a sensitive prognostic and postoperative recurrence marker in TC." (PMID 35406748, 2022). "There is, however, evidence that thyroglobulin gene (TG) mutations are more common in metastases than in primary tumours, which might result in lower iodine avidity in metastases." (PMID 34298840, 2021).
tumor (continued). "When adjusted for other variables, the factors significantly associated with preoperative serum thyroglobulin levels were age, sex (female), tumor histology (FTC), primary tumor size, number of LNM, positive resection margin, and presence of distant metastasis." (PMID 32182688, 2020). "Univariate analysis demonstrated that larger tumor size, higher level of pre-ablation stimulated thyroglobulin (sTg), intermediate to high risk stratification for recurrence, and lymph node and distant metastases were associated with a lower success rate of the first 131I ablation (all p < 0.05)." (PMID 30619772, 2018). "Tumor size, pathological tumor stage, lymph node (LN) metastasis, distant metastasis, American Thyroid Association recommended risks, pre-ablation thyroglobulin (Tg), and thyroid stimulating hormone (TSH) displayed significant differences between unsuccessful and successful group." (PMID 27721492, 2016). "In addition, they found greater mortality associated with larger tumor size, extrathyroid extension, lymph node involvement, male gender, external radiotherapy, iodine radioisotopes, high levels of thyroglobulin, and certain histological subtypes." (PMID 26115328, 2015). "Among these, miRNA-146 and miRNA-221 were validated as serum tumor biomarkers during post-surgical follow-up, showing a significant correlation with disease recurrence, even in patients with low thyroglobulin levels." (PMID 39850836, 2025). "The PTC tumor was generally positive for thyroglobulin (TG), whereas the main SCC component was TG‐negative." (PMID 40600748, 2025). "TD was significantly associated with preablative stimulated thyroglobulin (Ps-Tg), cumulative RAI dose, number of LNM, maximum tumor diameter, T stage, N stage, extent of extrathyroidal extension, and solitary/multifocal primary lesions." (PMID 40530009, 2025). "HMGA2-expressing thyrocytes were predominantly localized in areas of the tumor where the follicular structure was altered, whereas thyroglobulin staining was detected in the colloid of follicles that had retained their structure." (PMID 40004107, 2025). "Thyroglobulin (Tg), a thyroid-specific protein, is recognized as a specific tumor marker for the postoperative diagnosis and monitoring of persistent/recurrent disease in DTC." (PMID 39968066, 2025). "These tumor cells retain the ability to take up and organify iodine, as well as secrete thyroglobulin (Tg) in response to thyroid-stimulating hormone (TSH) stimulation." (PMID 39499416, 2025). "PET parameters were correlated to clinical parameters including tumor marker levels (thyroglobulin for DTC, calcitonin for MTC)." (PMID 39404789, 2025). "The nanogel, synthesized via rolling circle amplification and Mn-induced biomineralization, incorporated a thyroglobulin (Tg) aptamer for tumor-specific recognition." (PMID 41140492, 2025). "The follicular areas of the tumor were positive for thyroglobulin, thyroperoxidase, TTF1, and PAX8, supporting a follicular lineage, while the meaning of the morular structures is intriguing." (PMID 40892116, 2025). "Aggressive therapy is followed by serial monitoring of serum thyroglobulin levels and frequent whole body 131I scans as elevated serum thyroglobulin levels and iodine uptake are key markers for monitoring tumor recurrence." (PMID 41356641, 2025). "Immunohistochemistry demonstrated positive staining for thyroglobulin and thyroid transcription factor-1, confirming the thyroidal origin of the tumor." (PMID 40898513, 2025). "Immunohistochemical analysis showed positive staining for thyroglobulin and thyroid transcription factor-1, confirming the thyroidal origin of the tumor." (PMID 40898513, 2025). "Immunohistochemical staining revealed that the superficial epithelial cells were positive for thyroid transcription factor-1 and thyroglobulin, suggesting that the tumor originated from thyroid follicular cells." (PMID 41250727, 2025).
tumor (continued). "More than 90% of DTCs are PTCs, and thyroglobulin (TG), a key substrate for thyroid hormone production, is an important tumor marker for DTC." (PMID 40507982, 2025). "Clinical outcomes including local progression-free survival (LPFS), overall survival (OS), tumor response, serum thyroglobulin (Tg) levels, and adverse events were analyzed." (PMID 40917344, 2025). "Thyroglobulin (Tg), a glycoprotein produced exclusively by the follicular thyroid cells, serves as a reliable tumor marker for monitoring and managing patients with DTC after surgery." (PMID 39769016, 2024). "Thyroglobulin is the specific tumor marker for papillary and other types of epithelial thyroid cancer." (PMID 39766029, 2024). "Following thyroidectomy for thyroid cancer, serum thyroglobulin levels are measured as a tumor marker." (PMID 38501105, 2024). "The analysis of biomarker levels by tumor stage reveals a strong positive correlation between thyroglobulin and calcitonin levels and tumor progression across histopathological subtypes." (PMID 39767732, 2024). "Thyroglobulin (Tg) serves as a tumor marker for PTC, particularly useful for monitoring recurrence in patients who have undergone total thyroidectomy." (PMID 38598167, 2024). "The subject will follow a lifelong plan of periodical check-ups that include TSH and FT4 assays, along with tumour marker thyroglobulin serial testing." (PMID 39336834, 2024). "The progressive increase in thyroglobulin and calcitonin levels with advancing tumor stages across all histopathological subtypes demonstrates their utility as reliable indicators of disease progression." (PMID 39767732, 2024). "After surgery and radioiodine (RAI) therapy, monitoring of most patients with DTC is based on serum tumor markers (thyroglobulin and thyroglobulin antibodies) and neck ultrasound, with additional imaging required when a disease spread is suspected." (PMID 38837101, 2024). "Conversely, thyroglobulin levels were diminished in the solid pattern section of the tumor relative to the well-differentiated portion." (PMID 38598167, 2024). "The impact of various demographic, clinical, therapeutic, tumor-stage related, and histopathological variables on the achievement of undetectable thyroglobulin levels (uTg, <1 ng/mL) was studied." (PMID 39766029, 2024). "There were missing data in our study, including genetic analysis of SNPs, particular parameters of tumor histopathology, and particular measurements of thyroglobulin." (PMID 38755492, 2024). "It was further found that Ki-67 index and thyroglobulin expression outperformed tumour size and TNM staging as correlates to tumoural iodine avidity." (PMID 37284971, 2023). "Serum thyroglobulin levels correlate not only with tumor volume but also predict the lesion location." (PMID 36765880, 2023). "We found that the observed thyroglobulin DR was significantly lower than the hypothetical tumor volume DR before surgery (median 0.14/year vs. 2.0/year, p < 0.01)." (PMID 36153411, 2023). "The MTC tumor cells are generally positive for calcitonin, thyroglobulin, and neuroendocrine markers." (PMID 37234243, 2023). "Thyroglobulin (Tg) and calcitonin are commonly used as tumor biomarkers for several years regarding the postoperative follow-up evaluation of ThyC, according to the guidelines of the American Thyroid Association (ATA)." (PMID 37707688, 2023). "The risk factors associated with PTC recurrence include extrathyroidal extension, LN metastasis, multifocal tumor, high postoperative thyroid-stimulating hormone, and high postoperative anti-thyroglobulin antibody level." (PMID 37171355, 2023). "A composite tumor is one in which two discrete but closely adjacent cell groups in the same tumor focus individually express thyroglobulin and calcitonin." (PMID 37580706, 2023). "Tumor markers were evaluated in 18 patients, where two presented significantly high thyroglobulin (TG, >100 ng/mL)." (PMID 37174972, 2023).
tumor (continued). "Thyroglobulin is the most widely used tumor marker for differentiated thyroid cancer, but has several limitations." (PMID 36437732, 2023). "It has been found that radioisotopes should be performed postoperatively when MMFCC tumor tissue thyroglobulin (+) is present, as it is more effective in the treatment of local residual tumor, LNM foci < 1 cm in diameter, and small DM lesions." (PMID 37704803, 2023). "The AAbs-mediated interference in immunochemical assays was also described for circulating tumor markers CA-15.3, CA-125, and, most importantly, for thyroglobulin (TG), a tumor marker of DTC recurrence following primary treatment (see Section 4.2)." (PMID 35203677, 2022). "The tumor marker in DTC is human thyroglobulin, a glycoproteine synthesized by both healthy thyroid and DTC cells." (PMID 35735429, 2022). "The result was suggestive of a mesenchymal tumor constituted by spindle cells and vascular clefts, showing positivity for endothelial markers and negativity for thyroglobulin, calcitonin and TTF1." (PMID 35612841, 2022). "Some studies have found that the increase of serum thyroglobulin antibody(TgAb) in patients with PTC after surgery is related to tumor recurrence and metastasis." (PMID 36353227, 2022). "The patient underwent total thyroidectomy (pT3bN1a stage) and received one course of radioiodine (131I) 150 mCi, with a reduction in thyroglobulin levels of >50% and tumor growth control of lung metastatic bilateral lesions (up to 2 cm diameter)." (PMID 36202602, 2022). "In our study, we have found thyroglobulin to be a specific and sensitive tumor marker in cases of differentiated carcinoma of thyroid origin, namely papillary and follicular cancers." (PMID 35154933, 2022). "Serum thyroglobulin (Tg) levels in the blood and lymph node invasion are two major predictors of tumor development that must be monitored during long-term follow-up of DTC patients who have received RAIT." (PMID 36091039, 2022). "Thyroglobulin is a reliable tumor marker raised in both papillary and follicular tumors but is not specific." (PMID 35154933, 2022). "Serum thyroglobulin (Tg) is a sensitive tumor marker used in detection of residual and/or surveillance for recurrent DTC." (PMID 32794104, 2021). "Serum thyroglobulin (TG) and thyroglobulin antibodies (TGAb) are biochemical tumor markers used to monitor WDTC." (PMID 34829426, 2021). "Thyroglobulin values at all times correlated well with the baseline tumor stage and the therapeutic response evaluated at the end of follow-up." (PMID 33467717, 2021). "In terms of tumor markers, anti-thyroglobulin antibodies were within normal limits, while thyroglobulin was elevated (924 ng/ml)." (PMID 34274758, 2021). "Immunocytochemical staining techniques involve the utilisation of anti-thyroglobulin and anti-calcitonin antibodies to stain the tumours." (PMID 34910271, 2021). "Radioactive iodine therapy should be considered in cases of gross extrathyroidal extension, when the primary tumor is more than 4 cm, when there is extensive vascular invasion, or when post- operative unstimulated thyroglobulin levels are high." (PMID 34248855, 2021). "In the follow-up of DTC patients, thyroglobulin (Tg) is the most sensitive and specific tumour marker for the early detection of recurrence." (PMID 34975751, 2021). "The location of this non-synonymous polymorphism in the thyroglobulin (TY) domain of the EPCAM gene suggests its role in inhibiting cathepsins, a family of cysteine proteases that are frequently secreted by tumour cells during metastasis." (PMID 34573430, 2021). "Serum thyroglobulin (Tg) serves as a sensitive and easily available tumor marker for patients with metastatic differentiated thyroid carcinoma (m-DTC)." (PMID 34040584, 2021). "This emphasizes the importance of checking thyroglobulin level in unusual presentations (bone pain, fractures) of patients with neck swelling to help establish the primary source of the tumor." (PMID 34430179, 2021).
tumor (continued). "Several subsequent studies argued against these considerations and showed thyroglobulin expression in both parts of the tumor or at least in transition between follicular and insular structures." (PMID 32124226, 2020). "By immunohistochemistry, the tumor cells are positive for high- and low-molecular-weight keratins and usually positive for thyroglobulin, TTF1, and PAX8." (PMID 32632840, 2020). "The follicular epithelial origin of this tumor should be confirmed using immunohistochemistry including positivity for thyroglobulin (inset), thyroperoxidase, TTF1, PAX8, and cytokeratins (clone AE1/AE3)." (PMID 32632840, 2020). "Serum thyroglobulin levels were monitored after total thyroidectomies to reflect tumor burdens for most cases." (PMID 33117719, 2020). "The patient has been examined once a year, including the evaluation of tumor markers (most recent thyroglobulin levels 0.32 μg/l) and a sonograph of the neck." (PMID 31790949, 2020). "Tumor extent also increased with each decile of increasing preoperative thyroglobulin level (r = 0.18, p < 0.001)." (PMID 32182688, 2020). "We reviewed primary tumor size, number and location of LNM, and presence of distant metastases to reveal relationships between tumor burden and extent and preoperative serum thyroglobulin levels." (PMID 32182688, 2020). "Calcification is a result of a physiochemical reaction to altered thyroglobulin within the colloid of the tumor follicles." (PMID 33374707, 2020). "Follow-up of thyroid cancer usually consists of monitoring with ultrasound imaging of the neck and lab evaluation of thyroid function tests: mainly thyroid stimulating hormone (TSH) and tumor makers (thyroglobulin (Tg) and thyroglobulin antibody (TgAb))." (PMID 33153139, 2020). "Thyroglobulin (Tg) is a protein synthetized only by thyrocytes and released by both normal and tumor cells." (PMID 37362557, 2020). "The impact of other factors, including multifocality, age, tumor size, and stimulated thyroglobulin (sTg) values was also assessed." (PMID 32555991, 2020). "Until now, no conclusive studies had been conducted on the prognostic value of basal serum thyroglobulin levels in tumor progression during active surveillance." (PMID 31482955, 2019). "The complete thyroid resection allows the use of radioiodine for ablation of residual microscopic disease and subsequent use of thyroglobulin as tumor marker in recurrence monitoring." (PMID 31737363, 2019). "The primary endpoint of the study was to determine VA antitumor activity by evaluating measurable tumor response and/or decreased thyroglobulin levels." (PMID 31540307, 2019). "PTC progression was defined as the presence of i) a tumor larger than ≥ 3 mm, ii) novel appearance of lymph-node metastasis, and iii) serum thyroglobulin doubling time in less than one year." (PMID 31482955, 2019). "The drug showed promising activity, both in terms of thyroglobulin levels reduction and tumor shrinkage." (PMID 31540307, 2019). "Patients with malignancies tested positive for anti-thyroglobulin antibody (TGAb) and anti-thyroid peroxidase antibody (TPOAb) more frequently than those with benign nodules (TGAb, 30.3% vs. 15.0%, p < 0.001; TPOAb, 25.6% vs. 18.0%, p = 0.028)." (PMID 29514621, 2018). "This treatment also provides an increase in sensitivity of imaging methods and thyroglobulin (Tg), a specific tumor marker." (PMID 29858536, 2018). "Note, that the main goal of the proposed model is not only to describe the time course of thyroglobulin, but rather the tumor doubling time (Td) of the disease under RAI treatment." (PMID 28389624, 2017). "Adjuvant ablative RIT of thyroid remnants or tumor tissue is the optimal precondition for the follow-up including determination of serum thyroglobulin (Tg) and I-131 whole-body scans." (PMID 28629126, 2017).